BRCA1 (BRCA1 DNA repair associated)
Diseases named in the same sentence as BRCA1 in open-access papers (continued):
Sharing a sentence is not in itself a finding about the gene and the disease.
cancer (continued). "In sum, NANAC, A-443654, and CHIR-124 represent previously unknown agents for downregulating BRCA1 expression, which are largely unstudied in cancer treatment." (PMID 38993666, 2024). "As expected, genes including 53BP1 and PAXIP1 previously identified in murine models as synthetically viable in BRCA1/BRCA2-deficient tumors were not frequently altered in human cancers." (PMID 39198848, 2024). "Indeed, RAD51 foci were observed in the cancer cells from BRCA1/2 mutant patients that acquired PARPi resistance." (PMID 39007266, 2024). "Despite the evident link between HRD and BRCA1/2 mutations, it is now well established that the total number of HRD-H patients significantly exceeds the total number of BRCA-mutated patients in various cancer types." (PMID 39379982, 2024). "Notably, cancer cells harbouring BRCA1/2 PVs commonly rely on alternative repair pathways such as polymerase θ (POLQ)-mediated alternative end-joining and radiation sensitive 52 (RAD52)-mediated single-strand annealing." (PMID 39682099, 2024). "As a result, loss of RAD18 or UBC13 in BRCA1-deficient cancer cells does not abrogate reversed replication fork degradation, which is instead rescued upon knockdown of the fork reversal translocases SMARCAL1, ZRANB3 or HLTF." (PMID 38943334, 2024). "Treatment with JH-RE-06 leads to increased gap prevalence in BRCA1-mutant cancer cells." (PMID 38917325, 2024). "Our study assessed the expression of the selected main HR pathway genes in cancer tissue to check whether their mRNA levels are altered in the BRCA1/2mut BC." (PMID 39080120, 2024). "Interestingly, a recent pan-cancer research work also demonstrated an increase in T cells, natural killers, macrophages, and dendritic cells in BRCA2-mutated tumors, whereas BRCA1 mutant tumors exhibited a higher presence of myeloid suppressive cells." (PMID 38544832, 2024). "Our preliminary study does not support an association between serum zinc level and cancer risk in BRCA1 mutation carriers." (PMID 38790714, 2024). "We found that RAD18 knockout significantly diminishes cell viability in BRCA1-deficient but not BRCA1-proficient cancer cells." (PMID 38943334, 2024). "BRCA1/BRCA2, established tumor suppressors, have been observed paradoxically to inhibit cellular proliferation, which has been difficult to reconcile with their known cancer predisposition phenotype." (PMID 39198848, 2024). "Patients who have a BRCA1/2 variant, but were unaware and never underwent testing (eg, because of a decision not to undergo testing or if they died from cancer or a noncancer cause prior to testing) would not have been included in this study." (PMID 38916888, 2024). "Moreover, BRCA1 acts as a crucial indicator of the cancer’s potential to infiltrate and invade the immune system, which has important implications for developing targeted therapies in BRCA." (PMID 38224491, 2024). "PVs in BRCA1, BRCA2, CHEK2, and ATM have been linked to a wide variety of cancers." (PMID 38929805, 2024). "The molecular mechanisms underlying PARPi synthetic lethality in HR-deficient cancer cells beyond BRCA1/2 gene deficiencies have not been fully elucidated." (PMID 38807759, 2024). "One prospective, multicenter study included 2482 women with BRCA1 or BRCA2 P/LP variants from 22 centers in Europe and North America to assess the relationship of risk-reducing mastectomy or salpingo-oophorectomy with cancer outcomes." (PMID 39507757, 2024). "In this study, we present evidence demonstrating that BRCA1-suppressing agents may sensitize BRCA1-competent cancer cells to PARPi." (PMID 38993666, 2024). "Additionally, a family history of cancer, bilateral cancer, HER2-, and Ki67 ≥ 15% were identified as independent predictors of BRCA1/2 pathogenic variants." (PMID 38167124, 2024). "A BRCA1 variant disclosed to one individual (without prior personal or family history of BRCA-related cancer) was re-classified from LP to VUS during the study period after national variant discussions." (PMID 38131308, 2024).
cancer (continued). "PARP1 is best known for its clinical relevance in BRCA1-mutant cancers." (PMID 39730675, 2024). "PARP inhibitors that target PARP1/2, such as olaparib and talazoparib, have been approved as anticancer agents for patients with breast and ovarian cancers bearing mutations in the homologous recombination (HR) factors BRCA1 and BRCA2, as well as for platinum-sensitive cancers." (PMID 38625917, 2024). "Although BRCA1/2 is the most common genetic variant detected on germline testing, it is prudent to recognise non-BRCA HRR-related genes such as PALB2, ATM and RAD51 can also contribute to HBOC and other carcinomas." (PMID 39796639, 2024). "This is not yet standard of care because the true extent of the cancer risk reduction of salpingectomy alone in BRCA1/2 PV carriers is not yet known." (PMID 37887578, 2023). "From our NOP data, it is still controversial whether BRCA1, BRCA2, and MMR genes are associated with an increased risk of cancer in children and adolescents, and further studies are needed." (PMID 37916805, 2023). "Several prominent authors published a number of reviews on the hypotheses that may be suitable for the explanation of the remarkable tissue specificity of early cancers (HBOC) in BRCA1 and BRCA2 heterozygous carriers." (PMID 38275383, 2023). "The knowledge-based development of immunotherapy tailored to treat both inherited and sporadic MSI cancers, comes in addition to the knowledge-based development of PARP inhibitors to treat both inherited and somatic BRCA1/2 deficient DNA double-stranded break-associated cancer." (PMID 37821984, 2023). "Cells lacking BRCA1/2 show reduced proliferation, increased chromosomal aberrations, and increased susceptibility to cancer development." (PMID 35976445, 2023). "Our study shows that for cancer centres that use a tumour-first BRCA1/2 testing approach using the myChoice® CDx, around 5–10% of germline BRCA1/2 pathogenic variants may not be reported, all of which are likely to be pathogenic large rearrangements." (PMID 38201604, 2023). "In pathological comparisons, BRCA1 cancers tended to be triple-negative subtypes." (PMID 36905492, 2023). "PARPis were shown to be lethal in homologous recombination (HR)-deficient BRCA1/BRCA2-mutated cancers, likely because collapsed replication forks are no longer repaired." (PMID 36831435, 2023). "In clinical settings, BRCA1 and BRCA2 are linked to hereditary breast and ovarian malignancies." (PMID 37808268, 2023). "We suggest employing High-Resolution Melting Curve (HRM) real-time PCR as an affordable method to validate the extremely frequent pathogenic BRCA1/2 mutations in the most impacted exons in the blood of Egyptian CRC patients and their families as a non-invasive sample for cancer screening." (PMID 37804357, 2023). "Targeting BRCA1- and BRCA2-deficient tumors through synthetic lethality using poly(ADP-ribose) polymerase inhibitors (PARPi) has emerged as a successful strategy for cancer therapy." (PMID 37554969, 2023). "While these findings indicate that BRCA1 methylation may arise in normal cells subsequently developing into cancer precursors, several key questions need to be addressed." (PMID 38053165, 2023). "Accordingly, high-grade cancers also showed greater BRCA1/2 expression in earlier studies." (PMID 36899893, 2023). "Although the radio-sensitizing effect is expected to be higher in BRCA1/BRCA2-mutated cancers, PARPis were shown to synergize with RT regardless of the HR proficiency." (PMID 36831435, 2023). "Deletion of BRCA1 or BRCA2 induces the upregulation of TERRA RNA in cancer cells." (PMID 37108225, 2023). "Importantly, NVB selectively kills cancer cells harboring HR deficiency (BRCA1- and BRCA2-deficiency) and potentiates the cytotoxic effect of PARP inhibition in HR-deficient cancer cells." (PMID 37510250, 2023).
cancer (continued). "It further suggests that while RAD52 inhibitors may prove effective in treating cancers with BRCA1 defects, resistance may arise if tumor cells suppress EEPD1 expression or otherwise inactivate EEPD1." (PMID 38069223, 2023). "Alterations of BRCA1/2 and ATM may lead to homologous recombination deficiency (HRD), increasing the risk of breast‐, ovarian‐, prostate‐, and other cancers." (PMID 36653904, 2023). "Regaining HR proficiency can be achieved without affecting the BRCA1 mutation status, especially BRCA1 mutant cancers." (PMID 37892162, 2023). "However, further studies are required to determine the benefit of PARPi outside of the maintenance setting, and targeting of altered HRR genes other than BRCA1/2 should be evaluated in a wide range of cancer subtypes beyond PDAC." (PMID 38201431, 2023). "This approach could enable targeted reactivation of BRCA1, specifically in tumor cells, potentially restoring its tumor-suppressive function and inhibiting cancer progression." (PMID 37761820, 2023). "Small molecule Polθi is under development for the treatment of BRCA1/2 mutant cancers, and genotype-conferred sensitivity profiles could be useful for identifying optimal patient groups." (PMID 38001070, 2023). "Further analysis revealed that our population is enriched for pathogenic variants in ATM, BRCA1, and CDH1 genes and that prevalence of pathogenic variants in the CHEK2 gene is lower in the Slovenian population, when compared to GnomAD non-cancer control population." (PMID 37002323, 2023). "Although we had comprehensive cancer and treatment information, our study lacked data on family history of cancer, as well as reproductive and genetic factors, including BRCA1/2 and other mutation carrier status, and history of hysterectomy and oophorectomy." (PMID 37138341, 2023). "National Comprehensive Cancer Network (NCCN) evaluation and testing criteria for hereditary breast and ovarian cancer have relied primarily on the features of BRCA1/2-related cancers with a strong emphasis on age of diagnosis and strength of the cancer family history." (PMID 37084156, 2023). "BRCA1 and BRCA2, discovered in 1990s, are known cancer predisposition genes." (PMID 37020472, 2023). "An interesting finding was that the indication for genetic testing for 42% of patients without familial history of cancer was the TN histology revealing a BRCA1 mutation." (PMID 37239058, 2023). "Inhibition of PARP is a target in cancer treatment because its inhibition via RNA interference or chemical inhibitors can result in double-stranded breaks in replicating cells, leading to highly selective toxicity in BRCA1 and BRCA2 defective tumors." (PMID 36999995, 2023). "An aspect to consider is that although hysterectomy is not thought to be justified for cancer prevention in women with BRCA1 or 2 mutations, it can simplify later hormonal therapy to decrease the risk of BC or estrogen for menopausal symptoms." (PMID 36837501, 2023). "In addition, reliable VUS classification can also guide the cancer precision treatment, as hypersensitive to PARP inhibitors (Olaparib) was observed in tumors with loss-of-function BRCA1 mutations." (PMID 36593954, 2023). "Cancers associated with these genetic syndromes are currently treated with PARP inhibitors based on the exquisite sensitivity of cells lacking BRCA1 or BRCA2 function to inhibition of the PARP enzyme." (PMID 36975505, 2023). "These assays examine the ability of BRCA1 and BRCA2 variants to support cell viability, sensitivity to DNA damaging agents, ability to repair DSBs by HR, or to exhibit transcriptional activity and predict the role of mutations in cancer-predisposition." (PMID 37713444, 2023).
cancer (continued). "Its individualization is needed as BRCA1 mutations are basal, but not all basal cancers exhibit BRCA1 mutations." (PMID 36678877, 2023). "No comprehensible review on psychological morbidity in cancer-unaffected BRCA1/2 pathogenic variant carriers is currently available." (PMID 37185387, 2023). "The detection of BRCA1 promoter hypermethylation in BBLs reinforces this suggestion, knowing that a non-negligible rate of benign breast lesions was reported to evolve into cancer." (PMID 37761820, 2023). "One example of cancer dependencies that can be exploited therapeutically is the defect in the repair of DNA double-strand breaks (DSBs) through homologous recombination (HR) due to BRCA1 or BRCA2 inactivation." (PMID 37209095, 2023). "At the same time, according to some data from the literature, mutations in the BRCA1 and BRCA2 genes occur in 22–28% of cases; however, these values may vary depending on the type of cancer, ethnic group, and geographic location." (PMID 37628606, 2023). "Whereas in the past, germline testing focused on specific genes such as BRCA1 or BRCA2 to evaluate risk of breast, ovarian, and other cancers, over the past decade, there has been a shift to using multi-gene cancer panel tests that can reveal inherited risk for one or more cancer types." (PMID 37435610, 2023). "For example, 71% of the patients tested were female, which does not correlate with the sex-stratified incidence of LC and may be related to reported FH of BRCA1/2-related cancers in this group contributing to GGT." (PMID 37992258, 2023). "Similarly, improved outcomes have been observed with olaparib across a range of cancer histotypes harbouring BRCA1/2, or other HRR gene alterations." (PMID 37365284, 2023). "In these cancers, there are also distinct clinical phenotypes between BRCA1 and BRCA2 PVs carriers." (PMID 37025481, 2023). "Though PARP inhibitors are effective therapy for BRCA1/2-mutated cancers, not all patients respond, and most patients ultimately progress on PARP inhibitor therapy." (PMID 38069409, 2023). "In the present study, we found BRCA1 methylation in newborn girls to qualitatively and quantitatively mirror the one seen in adult cancer patients and previously recorded in healthy adults, indicating that the methylation observed in newborns and in adults is the same molecular feature." (PMID 38053165, 2023). "In total, 130 cancer samples with loss-of-function mutations in BRCA1/2 are labeled as HRD, while 1340 samples without inactivation mutations in known HR genes are labeled as homologous recombination proficiency (HRP)." (PMID 37193789, 2023). "How cancer cells achieve increased BRCA1-∆11q expression has remained unclear." (PMID 37491606, 2023). "Pedigree studies based on the UPDB have previously provided the identification of BRCA1 and BRCA2, and more recently have identified additional rare cancer predisposition variants (GOLM1; CELF4; FANCM; ERF; LRBA; FGF5) in similar sets of sampled high-risk pedigrees." (PMID 38136396, 2023). "This is similar to recent preclinical studies reporting that inhibiting different tyrosine kinase receptors or their downstream signaling transducers can sensitize cancer cells to PARPis by reducing expression of BRCA1, BRCA2, RAD51, and other HR components, thereby preventing HR repair." (PMID 37550562, 2023). "Genetics and cancer: This module provides basic information about the risk of developing HBOC-associated cancers with and without the contribution of BRCA1 or BRCA2 pathogenic variants and the modes of inheritance of these variants." (PMID 37760455, 2023). "Specifically, the clinical activity of ATR inhibition in PARP inhibitor (PARPi)-resistant tumors, including cancers with BRCA1/2 reversion mutations, has not been reported." (PMID 37277454, 2023). "So far, cancer-predisposition genes other than BRCA1/2 have not been studied in the population of Bahrain." (PMID 37656691, 2023).
cancer (continued). "The lower frequency of multipolar spindles in mitosis compared to amplified centrosomes in interphase in response to BAP1 or BRCA1 depletion may be explained by the ability of cancer cells to cluster amplified centrosomes to form pseudo-bipolar spindles." (PMID 36550359, 2023). "Regarding clinical actionability, the EXT1 variant has implications for differential diagnosis, the BRCA1 variant for therapy selection, and both the BRCA1 and the BRIP1 variants are clinically relevant for risk assessment, prevention, prophylaxis and early detection of their associated cancers." (PMID 36550207, 2023). "Mary-Claire King, who was the first to describe BRCA1, has suggested that genetic screening, of at least BRCA1/2, should be offered to every woman at around the age of 30 years, in order to detect healthy carriers prior to cancer onset." (PMID 37400873, 2023). "The dissection of specific protein functions within HR revealed that Polθi monotherapy may provide greater benefit for cancers with PALB2 and BRCA2 mutations relative to those with BRCA1 mutations." (PMID 38001070, 2023). "Identifying germline mutations in BRCA1 and BRCA2 genes would benefit the carriers by taking risk-reducing interventions before they get a cancer, as well as providing valuable information on the therapeutic application of Poly (ADP-ribose) polymerase inhibitors after a cancer occurs." (PMID 38274092, 2023). "In addition, HBOC is the most prevalent cancer syndrome identified in Qatar, accounting for ∼62% of all identified cancer syndromes, with BRCA1 being the most commonly involved gene." (PMID 37335020, 2023). "Moreover, using small interfering RNA-mediated knockdown of BRCA1 in human cancer cells resulted in decreased nuclear, cytoplasmic, and mitochondrial BRCA1 presence." (PMID 37109525, 2023). "If a BRCA1/2 PV is identified in a cancer patient, unaffected relatives may then be offered testing and access to prevention and screening." (PMID 37887578, 2023). "This theory is appealing, yet it is puzzling that other hormone-sensitive tissues (like the uterus, cervix, bone marrow, and brain) do not manifest increased cancer rates in BRCA1 mutation carriers." (PMID 38275383, 2023). "Similarly, among the 5,792 individuals within the nonindication-based cohort who had comprehensive multigene panel genetic testing, 12 (0.2%) had an AJ BRCA1/2 founder mutation, whereas 195 (3.4%) had a PLPV in any actionable cancer risk gene." (PMID 37535880, 2023). "The ability of PARPi to selectively eradicate HR-deficient cancer cells was first illustrated in cells lacking HR components BRCA1 and BRCA2 and provided the basis for the clinical development of PARPi." (PMID 37609662, 2023). "At a cellular scale, these BRCA1 functions coordinate tumor suppression, R-loop prevention, and cellular differentiation, all of which may contribute to BRCA1’s role in cancer tissue specificity." (PMID 37762577, 2023). "Taken together, these findings indicate that normal tissue BRCA1 methylation may arise as an early prenatal somatic event generating methylated subclones, resembling recent findings in respect to cancer-promoting embryonic PVs." (PMID 38053165, 2023). "This is consistent with a common clonal origin of methylated normal and cancer cells, which supports the hypothesis that these BRCA1-methylated tumors have arisen from BRCA1-methylated normal cells." (PMID 38053165, 2023). "In cancer EV-exposed BRCA1-KO fibroblasts, the expression of the cell cycle progression inhibitor CDKN1A and the cell death inducer mouse double minute 2 (MDM2) was decreased, whereas the expression of the oncogenes MYC and HRAS and the antiapoptotic factor BCL2L1 was increased." (PMID 37371036, 2023).